MST1R (macrophage stimulating 1 receptor)
Diseases named in the same sentence as MST1R in open-access papers (continued):
Sharing a sentence is not in itself a finding about the gene and the disease.
clear cell renal cell carcinoma (1 paper, 2017). "A two-gene methylation panel comprising OXR1 and MST1R identified malignancy with 98% sensitivity and 100% specificity, and clear cell renal cell carcinoma with 90% sensitivity and 98% specificity." (PMID 28662726, 2017). "A panel including OXR1 and MST1R promoter methylation allows specific and sensitive identification of renal cell tumors, and, especially, of clear cell renal cell carcinoma." (PMID 28662726, 2017).
coronary artery disease (1 paper, 2024). "Gene-based association tests and action-machine learning models identified MST1R as a significant genetic contributor to coronary artery disease." (PMID 40061823, 2024).
gallbladder cancer (1 paper, 2024). "To identify combination therapeutic targets in MST1R inhibitor MGCD-265-treated gallbladder cancer cells, we verified the top 30 up-regulated genes from transcriptomics sequencing using RT-qPCR." (PMID 39210450, 2024). "Given that the IC50 values of MGCD-265 were consistently below 1 μM for all three types of gallbladder cancer cells, it strongly suggests their heightened sensitivity to the MST1R inhibitor MGCD-265." (PMID 39210450, 2024). "In summary, this study explored the specific mechanism of MGCD-265 and the feasibility of combination therapy, confirming that the MST1R inhibitor MGCD-265 holds promise as a potential anti-gallbladder cancer drug." (PMID 39210450, 2024). "In this study, we screened MGCD-265, an MST1R inhibitor exhibiting anti-gallbladder cancer effects." (PMID 39210450, 2024). "The combined use of MST1R and JMJD6 inhibitors significantly enhances the anti-gallbladder cancer effect, potentially offering a viable combination therapy strategy for gallbladder cancer treatment." (PMID 39210450, 2024). "In this study, we observed that MGCD-265, a small molecule inhibitor targeting Recepteur d’Origine Nantais (MST1R, RON), exhibited a low IC50 value for gallbladder cancer cell lines." (PMID 39210450, 2024). "Furthermore, the concomitant utilization of MST1R and JMJD6 inhibitors manifested a synergistic anti-gallbladder cancer effect." (PMID 39210450, 2024). "Moreover, it consistently inhibits gallbladder cancer cell growth in vivo in a dose-dependent manner, underscoring the potential of MGCD-265, an MST1R inhibitor, to evolve into a potent anti-gallbladder cancer drug." (PMID 39210450, 2024).
hepatocellular carcinoma (1 paper, 2021). A malignant tumor that arises from hepatocytes. "miR892a modulates the FBLN1, MYH7B and MST1R genes and is known to promote proliferation and invasion of hepatocellular carcinoma cells via targeting CD226." (PMID 34357026, 2021).
insomnia (1 paper, 2024). A sleep disorder characterized by difficulty in falling asleep and/or remaining asleep. "Through SMR exploration of functional genes linked to frailty and insomnia in specific enriched tissues, four genes were identified: RMB6, MST1R, RF123, and FAM212A." (PMID 38425786, 2024). "The genetic correlation between frailty and insomnia showed enrichment in 11 brain regions (S-LDSC) and 9 brain regions (MAGMA), where four functional genes (RMB6, MST1R, RF123, and FAM212A) were identified." (PMID 38425786, 2024).
liver cancer (1 paper, 2018). An epithelial or non-epithelial malignant neoplasm that arises from the liver. "To determine whether DNA methylation alterations in the DMRs of Mst1r, Slpi, and Extl1 are involved in the expression of these genes, we assessed the effects of the DNA methylation inhibitor 5-aza-dC on the DNA methylation statuses and gene expressions in mouse liver cancer cell lines." (PMID 29566670, 2018).
Merkel cell carcinoma (1 paper, 2019). "As mutations within the tyrosine kinase domain of MST1R have been identified in Merkel cell carcinoma and Gastroesophageal adenocarcinoma, we screened DNA from our panel of MPM cell lines and the 17 fresh-frozen surgical samples for the presence of the R1018G or R1194H mutations." (PMID 30863365, 2019).
mesothelioma (1 paper, 2019). A usually malignant and aggressive neoplasm of the mesothelium which is often associated with exposure to asbestos. "In silico analysis of the TCGA mesothelioma dataset confirmed that high expression of MST1R and MST1 was associated with longer survival." (PMID 30863365, 2019). "We have identified a novel pathway, the MST1/MST1R (RON) signaling axis, which is overexpressed, activated, and can be targeted pharmacologically in mesothelioma." (PMID 30863365, 2019). "In contrast, a small molecule inhibitor of the MST1R (RON) tyrosine kinase domain (LCRF-0004) had significant effects on mesothelioma cellular proliferation and health, and cell cycle progression, and additions of exogenous MST1 were unable to abrogate these effects." (PMID 30863365, 2019). "These in silico analyses demonstrate that the MST1R and TYRO3 receptors are significantly overexpressed in mesothelioma, confirming previous data regarding MET and AXL, and suggesting that all four receptors may be candidate targets for therapy in MPM." (PMID 30863365, 2019). "This further strengthens the notion that receptors associated with macrophage signaling may have critical roles in mesothelioma pathogenesis, and it will be interesting in the future to determine if MST1R (RON) could heterodimerize with this RTK." (PMID 30863365, 2019). "While it is well established that the Hepatocyte Growth Factor Receptor (MET) is frequently overexpressed and activated in mesothelioma, to our knowledge this is the first indication that it's less well-studied family member, MST1R (RON) is also frequently activated in MPM." (PMID 30863365, 2019).
oncocytoma (1 paper, 2017). "Furthermore, in patients with low OXR1 and MST1R methylation level (NPV: 97%), HOXA9 methylation level distinguished oncocytoma from chRCC and pRCC." (PMID 28662726, 2017). "This performance is similar to that of OXR1 and MST1R methylation panel for RCT (98% sensitivity, 100% specificity), although this panel did not perform as well concerning oncocytoma vs RCC in general." (PMID 28662726, 2017).
psoriasis (1 paper, 2025). An autoimmune condition characterized by red, well-delineated plaques with silvery scales that are usually on the extensor surfaces and scalp. "Patients with psoriasis have hypomethylated human leukocyte antigen (HLA)-DMA and G protein-coupled receptor 128 (GPR128) genes, but they have hypermethylated tenascin-XB (TNXB) and macrophage stimulating 1 receptor (MST1R) genes." (PMID 40182929, 2025).
cancer (59 papers, 2004 to 2025). A tumor composed of atypical neoplastic, often pleomorphic cells that invade other tissues. "MST1R/RON emerged as a potential therapeutic target in various cancers because its activation has been implicated in contributing to resistance to treatment failure and resistance to cell death after chemotherapy or targeted therapies." (PMID 40560045, 2025). "In contrast, the MST1R/RON gene is involved in the tumor progression of various types of cancer, and GC mutations have been reported." (PMID 40028213, 2025). "The dysregulation of HGFR and/or MST1R were extensively implicated in multiple cancer oncogenic processes, such as proliferation, migration, invasion, angiogenesis, epithelial-to-mesenchymal transition (EMT) and drug resistance, etc." (PMID 36043496, 2022). "Point mutations in the MST1R kinase gene can activate the MET gene in human cancers releasing the oncogenic and metastatic potential of the receptor." (PMID 29056725, 2016). "Given this association and the increased expression in cancer, we posited that MST1R and MST1 genes may be co-regulated and that certain genomic alterations may dually affect expression." (PMID 35626096, 2022). "Loss of MST1R function may be a cancer susceptible marker for NPC." (PMID 34031426, 2021). "Considering the high frequent loss of MST1R had no obvious subtype and age preferences, it was suggested that MST1R loss may act as an early event of NPC by increasing oncogenic susceptibility associated with EBV infection, although the action of MST1R in other types of cancers might be opposite." (PMID 34031426, 2021). "Serval studies have demonstrated that TKIs can block MST1R and inhibited tumor proliferation, indicating that MST1R is a promising target for cancer therapy." (PMID 40424327, 2025). "HNRNPF contributes to cancer progression by regulating the splicing of oncogenic transcripts, such as the macrophage-stimulating 1 receptor (MST1R), leading to the activation of downstream signaling pathways implicated in tumorigenesis." (PMID 40724932, 2025). "The genes associated with cancer Hallmarks were GNAI2, RHOA, MAPKAPK3, HYAL1, and CISH, while the most connected were RHOA, MST1R, and ATRIP." (PMID 40028213, 2025). "MST1R (RON) is a receptor of the MET tyrosine kinase receptor family involved in several cancers such as pancreas, breast, ovary, colon, and stomach." (PMID 36361696, 2022). "Some studies have shown that overexpression of MST1R increases the migratory and invasive properties of cancer cells." (PMID 36361696, 2022). "Degraded macrophages (pro-MSP) can bind to MST1R and thus activate the signal transduction pathways involved in the propagation of cancer cells." (PMID 36361696, 2022). "The macrophage-stimulating RTK receptor 1 or MST1R, also known as RON (Récepteur d’Origine Nantais), gathered great interest concerning the fight against certain types of cancers such as pancreas, breast, ovary, colon, and stomach." (PMID 36361696, 2022). "An SE event in MST1R (macrophage stimulating 1 receptor) has been related to the acquisition of cell motility during cancer cell invasion." (PMID 32161615, 2020). "Aiming to target MST1R for cancer therapy, drugs such as tyrosine kinase inhibitors against the tyrosine kinase activity of MST1R and monoclonal antibodies against MST1R are being developed and some of these are under clinical trials or in research phases." (PMID 29566670, 2018). "Rare and possibly damaging variants were identified in 12 candidate genes in this cohort, including variants in DNA repair genes (ERCC1 and SXL4) and other cancer-related genes (NOTCH2, ERBB2, MST1R, and RAF1)." (PMID 29868112, 2018). "Such overexpression and activation of Mst1r are found in many types of human cancers and often correlate with poor prognosis in various cancers." (PMID 29566670, 2018).
cancer (continued). "Specific genes were highlighted for Hallmarks of Cancer NAG-related genes (PTPRJ and NDUFS) were linked to cell proliferation and growth; IGC genes (GNAI2, RHOA, MAPKAPK3, MST1R) to genomic instability, metastasis, and arrest of cell death; and DGC genes to energy metabolism and immune evasion." (PMID 40028213, 2025). "Then, we constructed a prognostic index for all cancer samples calculated by the formula IRGRS = expression level of EGFR*0.228279845567824 + expression level of OAS1*(-0.264868237274861)+expression level of MST1R*(-0.167523923476614)." (PMID 36267410, 2022). "Another mechanism that mediates cancer cell-macrophages crosstalk is driven by the recepteur d’origine nantais (RON) receptor [macrophage stimulating 1 receptor (MST1R)] which is a member of mesenchymal-epithelial transition factor (MET) family of receptor tyrosine kinases." (PMID 36338516, 2022). "Regulation of genes that are known to be associated with cancer (VEGFA, DDX58/RIG1, MST1R/RON, BAGE, and TPTE) in anti‐TIF‐1γ+ patients, and their expression on protein level, however, need further investigation as these genes are also involved in other biological processes apart from tumorigenesis." (PMID 34043263, 2021). "Besides alterations in these cancer hallmark genes, SNVs were identified in the less characterized genes GRM3, MST1R, PRKN, and PIK3C2G." (PMID 34399808, 2021). "Several molecules promoting cancer cell invasion and metastasis have been identified, of which recepteur d’origine nantais (RON), encoded by the macrophage stimulating protein receptor (MST1R) gene, is very important." (PMID 31906413, 2020). "We selected genes which are statistically significantly up or down regulated more than 10 fold by overexpression of Mst1r or Slpi, also show the same direction of significant expression changes in the liver tumors of C3H mice, and are found to be related with “cancer” by a PubMed search." (PMID 29566670, 2018). "While additional work is needed to assess the functional relevance of both PEAK1 and MST1R in the context of KRas wild type cancers, these data predict that PEAK1 may be a more potent driver of initiation and progression under these wild type KRas conditions." (PMID 27602776, 2017). "MST1R, a homologue of MET, orchestrates cell signaling pathways that foster tumorigenesis, cancer cell survival, and growth." (PMID 39210450, 2024). "Recognized cancer-related kinases are again observed in this set, including ERBB2, FGFR2, PTK6, RAF1 and RON (MST1R) as well as 22 understudied kinases." (PMID 29643987, 2018). "Proliferation and invasion of cancers were increased by FOXC1 by mediating NF-κB, MST1R and KLF4 expression." (PMID 29552326, 2018). "Of those, we highlight four genes related to cancer development and progression (NOTCH2, ERBB2, MST1R, and RAF1) and two DNA repair genes (ERCC1 and SLX4)." (PMID 29868112, 2018). "We analyzed data from The Cancer Genome Atlas (TCGA) Pan-Cancer (PanCan) datasets and found a significant positive correlation between MST1R and MST1 expression in all available cancer type datasets except liver hepatocellular carcinoma (LIHC), where MST1R/MST1 are negatively correlated." (PMID 35626096, 2022). "Studies herein are the first to report correlated co-expression of MST1R and MST1 across nearly all cancer types and are consistent with a previous study that reported a lack of alterations using polymerase chain reaction-single strand conformational polymorphism (PCR-SSCP) analysis." (PMID 35626096, 2022). "Previous findings demonstrated that the transcription of full-length and short-form Ron is initiated by the two independent promoters within RON (MST1R) gene, each regulated by distinct epigenetic mechanisms that leads to an independent expression of Ron isoforms in malignant tumors." (PMID 33488949, 2020). "Moreover, both 3p21.3 (MST1R) and 20q13 (PTK6) contain putative oncogenes, which are frequently located in regions of genomic amplification in cancer." (PMID 16508639, 2006).
cancer (continued). "Upregulation was observed in many genes, including CAV2, FGFBP1, KRT19, MST1R, OCLN, and RGS2, which play important roles in the negative regulation of EMT and metastasis phenotypes in many cancers." (PMID 37298519, 2023).
tumor (58 papers, 2008 to 2026). "IL33 was also upregulated in the tumor tissues of C3H mice and its expression is associated with MST1R expression in higher MST1R expressing group." (PMID 29566670, 2018). "We predict that this new mH-based RNA extraction method can now be applied to evaluate tumor-specific factors that can regulate the splicing and tumorigenic potential for MST1R and other genes associated with PDAC." (PMID 27602776, 2017). "Mechanistically, MST1R inhibitors predominantly exert anti-tumor effects by suppressing the expression of downstream genes, including members of the MMP family or genes associated with the PI3K pathway." (PMID 39210450, 2024). "The RON receptor tyrosine kinase (MST1R) is expressed at high levels at the surface of many tumor cells of epithelial origin." (PMID 36581692, 2022). "MST1R was related to cellular motility and matrix invasion that are the predictive indications of a tumor phenotype with the ability to metastasize." (PMID 36072903, 2022). "We also detected other epigenetically regulated genes in this signature, including CD70, IRAK, IL20RA, THBD, TACSTD2, and MST1R, with implications related to the tumor immune microenvironment." (PMID 34150764, 2021). "Mst1 mRNA levels were significantly higher in KB1P tumors, but Mst1r levels (measured by primers that identify all isoforms) were the same between tumor models." (PMID 32484599, 2020). "We also measured gene expression levels of the normal and tumor tissues by real-time PCR and confirmed up-regulation of Mst1r and Slpi and down-regulation of Extl1 in the tumor tissues." (PMID 29566670, 2018). "Mst1r activation is involved in tumor augmenting signaling pathways, such as the PI3K/AKT and RAS/ERK pathways." (PMID 29566670, 2018). "While PEAK1 is upregulated in both genetic backgrounds within PDAC cells under physiologically relevant tumor microenvironment conditions (i.e., the orthotopic site in nude mice), MST1R is only upregulated in KRas mutant cells implanted at this site." (PMID 27602776, 2017). "MST1, the ligand for MST1R, was also elevated at the mRNA level in tumor samples." (PMID 38212428, 2024). "In our analysis, the receptors MET and MST1R displayed increased mRNA expression in tumor samples." (PMID 38212428, 2024). "Besides, MST1R (AUC = 0.811), CAPG (AUC = 0.743), CLEC18A (AUC = 0.714), and EMT score (AUC = 0.700) also had significant diagnostic accuracy in distinguishing tumor and normal samples." (PMID 36072903, 2022). "The gene expression levels of CAPG, CLEC18A, and MST1R were higher in the tumor samples." (PMID 36072903, 2022). "Driver gene alteration status (Altered or Unaltered) was used to stratify tumor samples, and the difference in means of MST1R and MST1 expression individually were compared across Altered/Unaltered status using samples from the TCGA PanCan and METABRIC datasets." (PMID 35626096, 2022). "Of note, one of the most notable common features is that they all lose MST1R at an extreme high frequency (55.6%), indicating that MST1R may act as a tumor suppressor in NPC, contrary to the carcinogenic effects of MST1R in other types of cancer." (PMID 34031426, 2021). "A previous publication exhaustively characterized copy number alterations in tumors from the KP and KB1P models and showed that allele frequency of Mst1 and Mst1r genes is normal in both tumor types, without amplification or deletion." (PMID 32484599, 2020). "Mechanistically, PDGFRα, EGFR, IGF-IR, and macrophage-stimulating 1 receptor (MST1R) were activated in decorin-deficient mice, suggesting that decorin acts as a secreted tumor suppressor during hepatocarcinogenesis by hindering the action of another receptor tyrosine kinase." (PMID 30297672, 2018).